PPM1J (protein phosphatase, Mg2+/Mn2+ dependent 1J)
Synonyms: PP2C-zeta; PPP2CZ; FLJ35951; MGC19531; DKFZp434P1514; PP2Czeta; PP2CZ
Tractability: PROTAC: ubiquitination databases record sites on it.
Gene: Protein-coding gene on chromosome 1 (112,709,994 to 112,715,336, reverse strand). Ensembl gene ENSG00000155367.
Subcellular location (Human Protein Atlas): Vesicles
Gene Ontology:
Molecular function: protein binding; protein serine/threonine phosphatase activity
Genetic constraint (gnomAD): Loss-of-function variants: 40 observed, 48.8 expected, observed/expected ratio (o/e) 0.82, 90% interval 0.64 to 1.07. The upper end of that interval is the gene's LOEUF score, 1.07, which puts it in group 4 of 6, group 1 being the genes least tolerant of losing a copy. Missense variants: 633 observed, 624.36 expected, observed/expected ratio (o/e) 1.01, 90% interval 0.95 to 1.08. Synonymous variants: 267 observed, 255.5 expected, observed/expected ratio (o/e) 1.04, 90% interval 0.94 to 1.16.
Homologues: Orthologues: chimpanzee PPM1J (99% identical), dog PPM1J (94% identical), pig PPM1J (94% identical), guinea pig PPM1J (93% identical), rabbit PPM1J (90% identical), mouse Ppm1j (88% identical), rat Ppm1j (85% identical), macaque PPM1J (83% identical), zebrafish ppm1h (53% identical), zebrafish ppm1j (53% identical), Drosophila melanogaster CG17598 (39% identical), Caenorhabditis elegans ppm-1.H (36% identical), and 12 more. Paralogues in human: PPM1H (55% identical), PPM1M (40% identical), PPM1E (19% identical), PPM1F (18% identical), PDP2 (17% identical), PPM1N (17% identical), PP2D1 (16% identical), PPM1B (16% identical), PDP1 (16% identical), PPM1A (16% identical), PPM1K (15% identical), PPM1L (15% identical), and 4 more.
Diseases named in the same sentence as PPM1J in open-access papers:
PPM1J is named in the same sentence as 4 diseases in open-access papers, as found by Europe PMC text mining. Sharing a sentence is not in itself a finding about the gene and the disease. The quoted sentences say what the papers report.
glaucoma (1 paper, 2022). Increased pressure in the eyeball due to obstruction of the outflow of aqueous humor. "For example, CDCA8, HLA-B, RHOC, PPM1J, RPL10A, and TEAD3 are associated with glaucoma (P < 1 × 10−6)." (PMID 36450729, 2022).
neuroblastoma (1 paper, 2024). Neuroblastoma (NB) is the most common solid, extracranial childhood tumor. "We noted that LRIG2 SVA dosage was associated with contrasting effects on PPM1J expression in our ΔSVA SH-SY5Y cell lines and in the NABEC data, and postulate that this may be due to phenotypic differences between SH-SY5Y neuroblastoma cells and the frontal cortex tissue collected in NABEC samples." (PMID 38191889, 2024).
staphylococcus aureus infection (1 paper, 2021). An infectious process in which the bacteria Staphylococcus aureus is present. "PPM1J is involved in the response of Staphylococcus aureus infection." (PMID 34723755, 2021).
PPM1J also shares sentences with these, for which no sentence is quoted: neurodegenerative disease (1 paper).